ZFAS1 (ZNFX1 antisense RNA 1)
Diseases named in the same sentence as ZFAS1 in open-access papers (continued):
Sharing a sentence is not in itself a finding about the gene and the disease.
cancer (continued). "The regulatory functions of the ZFAS1/miRNA/mRNAs axis might provide a prognostic and therapeutic biomarker for cancers." (PMID 40109869, 2025). "We believe that the intricate relationship among the ZFAS1-miRNA-mRNA axis may yield potential therapeutic targets for effective cancer management." (PMID 40109869, 2025). "Also, the role of ZFAS1 in several cancers has been well studied in vitro, but very few in vivo models have been investigated." (PMID 40109869, 2025). "In addition, knockdown of the ZFAS1 has been shown to significantly alter the metabolic profile of cancer cells." (PMID 40697388, 2025). "Furthermore, the Pearson correlation coefficient shows that ZFAS1 interacts with multiple miRNAs such as miR-497-5p, miR-150-5p, miR-124-3p, miR-589-5p, and miR-7-5p and is dysregulated in various cancers." (PMID 40109869, 2025). "ZNFX1 Antisense RNA 1 (ZFAS1) act as an oncogenic long noncoding RNA in multiple types of cancer." (PMID 39296014, 2024). "Yet the ZFAS1 levels typically differed depending on the cancer stage and tumour size (T-stage)." (PMID 37628760, 2023). "The LncRNA ZFAS1 is upregulated in several cancers and may contribute to the development and progression of these cancers." (PMID 36770654, 2023). "However, most recent studies have mainly revealed that ZFAS1 participates in the multilayered biological functions of cancer cells, such as proliferation, metastasis, and chemoresistance, by regulating miRNAs." (PMID 35036050, 2022). "ZFAS1 lncRNA is a major protein regulator involved in various human cancers, including COAD." (PMID 36545127, 2022). "ZNFX1 antisense RNA1 (ZFAS1) is overexpressed in a variety of cancers, including CRC." (PMID 35036050, 2022). "For instance, lncRNA ZFAS1 was higher in cancer tissues and could be transmitted between cancer cells via exosomes in ESCC." (PMID 36591473, 2022). "The ZFAS1/DDX21/POLR1B signaling regulation axis may also be a new biomarker for targeted CRC treatment, where ZFAS1 knockdown dramatically reduced cancer cell properties and increase apoptosis." (PMID 34262080, 2021). "This indicates that ZFAS1 is a major regulator of cancer aggressiveness and could be a target for therapeutic intervention in the future." (PMID 33771981, 2021). "Notably, the lncRNA zinc finger antisense 1 (ZFAS1) has been identified to promote cancer development." (PMID 34249125, 2021). "In addition, non-coding host genes have recently been found to be involved in cancer onset or progression, for example ZFAS1, GAS5, and MEG8." (PMID 32046192, 2020). "Although there are already studies on ZFAS1 in other cancers, few ZFAS1-related studies in PAAD have been published, and the expression level and underlying molecular mechanism of ZFAS1 in PAAD remain unknown." (PMID 32550827, 2020). "LncRNA ZFAS1 is a newly discovered lncRNA which is downregulated in human breast cancer, and it may serve as a cancer-inhibiting factor." (PMID 31775815, 2019). "Therefore, we propose that upregulated ZFAS1 promotes cancer cell migration via elevating cellular ROS production by repressing the expression of NADH dehydrogenases, including NDUFA6, NDUFB4, and NDUFB11." (PMID 31781169, 2019). "Fourth, one cancer-related translated lncRNA, ZFAS1, was found to play important roles in promoting cancer cell migration and affecting cell metabolism in HCC, which indicated that our method could identify cancer-related translated lncRNAs." (PMID 31781169, 2019). "Accumulated data indicate a possible oncogenic role for ZFAS1 in cancer transformation." (PMID 31010087, 2019). "Therefore, ESCC cells transmit ZFAS1 to surrounding cancer cells through exosomes, which affects the development of ESCC." (PMID 31775815, 2019). "In the group of patients with low expression of ZFAS1, we detected the up-regulation of suppressors and down-regulation of genes associated with epithelial-to-mesenchymal transition (EMT) process, metastases, and cancer-initiating cells." (PMID 31010087, 2019).
cancer (continued). "Overexpression of ZFAS1 in various cancers has been shown to exert oncogenic functions through regulating cancer-related phenotypes, such as promoting cell proliferation, migration, invasion, inhibiting apoptosis in different cancer types." (PMID 30186041, 2018). "Several meta-analyses were conducted to assess the prognostic value of ZFAS1 in human cancers, and suggested that ZFAS1 high expression might act as a credible factor for unfavorable clinical outcome in various human malignancies." (PMID 29678899, 2018). "Results suggested that ZFAS1 overexpression was significantly associated with shorter OS, DFS, and RFS in human solid tumors, indicating that ZFAS1 was considered as a prognostic marker for cancer patients." (PMID 30544408, 2018). "Therefore, a meta-analysis was conducted to further investigate the relationship between clinicopathological features and the prognostic significance of ZFAS1 expression in various cancers." (PMID 30544408, 2018). "Results revealed that the overexpression of ZFAS1 was significantly associated with poor OS (HR = 1.97, 95% CI: 1.53–2.54), worse RFS (HR = 1.95, 95% CI: 1.24–3.04) and worse DFS (HR = 2.35, 95% CI: 1.43–3.88) in cancers." (PMID 30544408, 2018). "The role and biological functions of lncRNA ZFAS1 are different in various cancers." (PMID 30544408, 2018). "Furthermore, since our aim was to gain a general insight into the overall prognostic value of ZFAS1 expression in cancer patients, this study included different types of cancer." (PMID 29163829, 2017). "In conclusion, this meta-analysis suggested that lncRNA ZFAS1 might serve as a prognostic biomarker for cancer patients." (PMID 29245995, 2017). "Our results suggested that lncRNA ZFAS1 might serve as a novel molecular marker for clinical progression and prognosis for cancer patients in China." (PMID 28977885, 2017). "Taken together, our meta-analysis results indicate that ZFAS1 may act as a novel biomarker in predicting the clinical outcome of cancer patients." (PMID 29137442, 2017). "The results showed that cancer patients with high ZFAS1 expression had a worse OS than those with low ZFAS1 expression (HR: 1.94, 95% confidence interval [CI]: 1.41–2.47, P < 0.001), and high ZFAS1 expression was significantly associated with LNM (OR: 2.60, 95% CI: 1.54–4.42, P < 0.001)." (PMID 29137442, 2017). "In conclusion, lncRNA ZFAS1 might serve as a prognostic biomarker for cancer patients and increased ZFAS1 expression may be closely related to advanced characteristics of cancer." (PMID 29245995, 2017). "In conclusion, the present meta-analysis demonstrates that high ZFAS1 expression may potentially serve as a reliable biomarker for poor clinical outcome in various cancers." (PMID 29137442, 2017). "Furthermore, silibinin targets long non-coding RNA: HOTAIR and ZFAS1, which are known to play roles as oncogenic factors in various cancers." (PMID 29190895, 2017). "Additionally, studies are needed to confirm the specific functions of ZFAS1 in different kinds of cancers." (PMID 28977885, 2017). "In summary, our meta-analysis demonstrates that elevated ZFAS1 expression correlates with poor prognosis in cancer patients, suggesting that ZFAS1 might serve as a potential molecular target for cancer prognosis." (PMID 29163829, 2017). "This meta-analysis was to investigate the prognostic role of lncRNA ZFAS1 in cancer patients." (PMID 29245995, 2017). "This current meta-analysis was performed to explore the correlation of ZFAS1 expression with clinical outcome of cancer patients, and further determine whether ZFAS1 could serve as an effective biomarker for metastasis and prognosis." (PMID 29137442, 2017). "Moreover, silibinin suppressed the expression of lncRNA HOTAIR and ZFAS1, which are reported to promote several types of cancers." (PMID 29190895, 2017). "Thus, we conducted a systematic review and meta-analysis to explore the prognostic role of ZFAS1 in cancers patients." (PMID 29245995, 2017).
cancer (continued). "Furthermore, elevated expression of ZFAS1 has been associated with worse overall survival (OS) and recurrence-free survival (RFS) rates in cancer patients." (PMID 29163829, 2017). "Therefore, this meta-analysis was performed to comprehensively elaborate the prognostic value of ZFAS1 as a candidate biomarker for human cancer." (PMID 28977885, 2017). "Thus, our study aimed to assess the prognostic value of ZFAS1 in cancer patients via a meta-analysis." (PMID 28977885, 2017). "Thus, we demonstrated, in human cancer tissues, that expression of ZFAS1 is closely correlated with EMT process of GC, which can potentially be targeted for treatment of GC." (PMID 27654478, 2016). "Thus, it is possible that ZFAS1 plays different roles in different type of cancers, and the mechanism requires further investigation." (PMID 27654478, 2016). "Here we selected 14 candidate cancer-related lncRNAs (ZFAS1, PVT1, PRNCR1, lncRNA-ATB, HOTAIR, MALAT1, NKILA, TUG1, lnc-MVIH, HULC, lnc-HEIH, UFC1, UCA1 and H19) from previous literatures and a database(LncRNA Disease database) that integrated published lncRNAs and their associated diseases." (PMID 27654478, 2016). "As the scientific community continues to investigate the multifaceted functions of ZFAS1, its potential as a prognostic biomarker and therapeutic target remains an area of significant interest, as it is promising for enhancing our understanding of cancer pathogenesis and treatment strategies." (PMID 39335515, 2024). "However, the expression status and specific role of ZFAS1 involved in cancer progression of human HB remain unknown." (PMID 31781561, 2019). "Functional studies revealed that ZFAS1 can promote cancer cell migration by elevating intracellular reactive oxygen species production by inhibiting nicotinamide adenine dinucleotide dehydrogenase expression, indicating that translated ZFAS1 may be an essential oncogene in the progression of HCC." (PMID 31781169, 2019). "Similarly, the over-expression of ZFAS1 in tissue from other cancers was also described." (PMID 31010087, 2019). "Additionally, the depletion of ZFAS1 could substantially suppress the proliferation, invasion and migration of cancer cells, while the overexpression of ZFAS1 could markedly promote the tumorigenesis and metastasis." (PMID 29245995, 2017). "Furthermore, increased ZFAS1 expression may be closely related to advanced characteristics of cancer." (PMID 29245995, 2017). "The authors claim that ZFAS1 might be seen as a developmental gene (given its downregulation from pregnancy to lactation), and since many developmental genes are involved in cancer, it is worthwhile to investigate ZFAS1 in the context of cancer cells." (PMID 27871336, 2016). "ZFAS1 may promote cancer invasion and metastasis by regulating EMT and CTCs." (PMID 27654478, 2016). "While ZFAS1's pathway crosstalk in HCC remains partially characterized, its pan-cancer regulatory versatility reveals therapeutic promise." (PMID 41450817, 2026). "It has been established that ZFAS1 interacts with STAT3, a widely recognized oncogenic transcription factor involved in the development and progression of cancer in TNBC cells." (PMID 41459628, 2026). "The current findings build upon this by revealing the interplay between ZFAS1, IGF2BP2, and STAT3, which appears to be an important mechanism driving cancer progression." (PMID 40697388, 2025). "The IMP2-ZFAS1-OLA1 axis is instrumental in CRC progression by stabilizing ZFAS1 and enhancing OLA1 activity, which in turn accelerates glycolytic metabolism and supports cancer cell proliferation and survival." (PMID 40141058, 2025). "However, it is unclear whether ZFAS1 is involved in the ferroptosis of cancer cells." (PMID 39296014, 2024). "LncRNA ZFAS1 is another important RNA identified in GC-derived exosomes, and has been shown to impact MAPK signaling, EMT, cell cycle progression, as well as cancer growth and metastasis." (PMID 38743146, 2024).
cancer (continued). "ZFAS1 knockdown can suppress cancer cell cycle progression, induce apoptosis, and inhibit EMT, while high levels of exosomal ZFAS1 can promote GC cell proliferation and migration." (PMID 34819615, 2021). "The ZNFX1 antisense RNA 1 (ZFAS1) lncRNA located on chromosome 20q13 is another lncRNA involved in progression and metastasis of various cancers." (PMID 33980320, 2021). "ZnFX1 antisense RNA 1 (ZFAS1) belongs to lncRNA and has been reported to promote the occurrence and development of a variety of cancers." (PMID 34604208, 2021). "Previous studies have shown that lncRNA ZFAS1 plays an oncogenic role by interacting with EZH2 in GC and is also upregulated in HNSCC because it is positively related to cancer initiation and metastasis." (PMID 34249125, 2021). "Examples of this are HOXD-AS1 and ZFAS1 function in invasion and metastasis, HULC in cell metabolism and proliferative signaling or H19 in both the maintenance of cancer stem cells and angiogenesis." (PMID 34071216, 2021). "The lncRNA ZFAS1, the antisense transcript of the gene ZNFX1, is abnormally expressed in many cancers." (PMID 32550827, 2020). "ZFAS1, as a novel star lncRNA candidate after HOTAIR and MALAT1, is abnormally expressed in various cancers; however, few ZFAS1-related studies on PAAD have been published." (PMID 32550827, 2020). "We report the up-regulation of ZFAS1 in HNSCC cell lines and cancer tissue samples derived from patients." (PMID 31010087, 2019). "ZFAS1 is described as a modulator of the EMT process, cancer-initiating cell maintenance, and metastasis in many cancers, so its role in HNSCC was also checked." (PMID 31010087, 2019). "However, the exact role of ZFAS1 lncRNA remains unknown in some cancers, including the HNSCC." (PMID 31010087, 2019). "Previous studies have indicated the role of ZFAS1 in the regulation of EMT process, migration, and influence on cancer-initiating cells in different cancer types." (PMID 31010087, 2019). "Therefore, ZFAS1 may be involved in other aspects of cancer hallmarks apart from cell mobility." (PMID 31781169, 2019). "Examples include patients with high level of ZFAS1 with low expression of NOTCH1, one of the important elements of the pathway described in the context of EMT and cancer-initiating cells." (PMID 31010087, 2019). "Through searching the published literatures, six lncRNAs (ZFAS1, PRNCR1, GAS5, TUG1, linc-ROR, H19) which have been reported to be abnormally expressed in cancer were included in the present study." (PMID 29559565, 2018). "Here we selected six candidate cancer-related lncRNAs (ZFAS1, PRNCR1, GAS5, TUG1, linc-ROR, and H19) through articles that were previously reported to be dysregulated in cancer." (PMID 29559565, 2018). "Several lncRNAs have been confirmed to play an important role in various types of malignant tumors, including PANDAR, ZFAS1, HOTAIR, TUG1 and so on23–26." (PMID 30111807, 2018). "First, similar to several other lncRNA markers, both ZFAS1 and CDR1AS were found to be upregulated in cancer patients, suggesting that cancer is a confounder and might hamper ZFAS1 and CDR1AS diagnostic specificity." (PMID 38188000, 2023). "At the molecular level, ZFAS1 binds miR-150-5p, the inhibitor of eIF4E (eukaryotic translation initiation factor 4E), which is required for the translation of several genes involved in proliferation, survival, EMT, and cancer invasion." (PMID 37628760, 2023). "Interestingly, ZFAS1 was negatively correlated with ZEB2, while NORAD was positively correlated with ZEB2 in PRAD cancer type." (PMID 36514044, 2022). "In addition, previous studies confirmed that lncRNA ZFAS1 acts as an oncogene gene to promote the growth and metastasis of multiple solid tumors by mediating the EMT and proliferation of cancer cells." (PMID 32453709, 2020). "Cancer-relevant mRNAsBIRC5 (Survivin) andYBX1,as well as long-noncoding RNAsHOTAIR,ZFAS1, andAGAP2-AS1 were detected in BT-474 EVs by quantitative RT-PCR." (PMID 33447385, 2020).
cancer (continued). "Analyses stratified by sample size, cancer type, HR obtain method and sample size did not alter the significant predictive value of ZFAS1 in OS from various cancers." (PMID 30544408, 2018). "However, there is controversy about the relationship between ZFAS1 expression and LNM in various cancers." (PMID 29137442, 2017). "Nevertheless, the prognostic value of ZFAS1 in cancer has not yet been fully elucidated, and systematic studies are lacking." (PMID 29163829, 2017). "What do the authors conclude, other that ZFAS1 and ZNFX1 are expressed in both normal and cancer?" (PMID 27871336, 2016). "During the course of our work, others have reported investigations on ZFAS1 in different cell types (including cancer cells,) and have described mechanisms of action that do not seem to pertain to the cell type we are investigating." (PMID 27871336, 2016). "Although derived from non-HCC models, these findings collectively establish ZFAS1's evolutionary conservation in coordinating malignancy through core mechanisms (miRNA sequestration/pathway networking), providing trans-cancer insights for deciphering its HCC regulatory architecture." (PMID 41450817, 2026). "Finally, we found through the detection of epithelial-mesenchymal transition (EMT)-related genes that interfering with the expression of ZFAS1 can significantly affect the EMT process, which may be one of the reasons for its cancer-promoting effect (p < 0.05)." (PMID 34980191, 2022). "Third, ZFAS1 expression was measured by RT-qPCR in all enrolled studies and the cut-off definition of high and low expression in cancer tissues was not always consistent, which may affect the results and potentially contribute to heterogeneity." (PMID 30544408, 2018). "In conclusion, this meta-analysis revealed that the elevated expression of lncRNA ZFAS1 may be a negative factor when assessing the clinical outcome of cancer patients." (PMID 30544408, 2018). "From the available studies, we found that high ZFAS1 expression was associated with poor OS in different types of cancers without significant heterogeneity, suggesting that ZFAS1 may serve as a reliable molecular marker for poor prognosis in various cancers." (PMID 29137442, 2017). "Furthermore, silibinin may exert its anti-cancer effects by suppressing oncogenic lncRNAs such as HOTAIR and ZFAS1." (PMID 29190895, 2017). "In order to verify whether ZFAS1 exerts a cancer-promoting effect through miR-100-3p, we tested that overexpression of miR-100-3p can reduce the viability and migration ability of NPC cells, and this phenomenon was reversed after overexpression of ZFAS1 (all p < 0.05)." (PMID 34980191, 2022). "Importantly, such gain-of-function mutations may occur at regulatory elements not annotated in the cancer tissue-of-origin (in this case liver) but in regulatory elements active in other cell types (for example, ZFAS1 in breast tissue)." (PMID 28333948, 2017). "ZFAS1 and GAS5, but not SNHG5 and SNHG8 were significantly upregulated in cancer tissues in HCC patients." (PMID 34072570, 2021). "Specifically, in obese subjects we found several lncRNAs (e.g., ZFAS1, LUCAT1, HIF1A-AS1, HOXB-AS3) already identified in the setting of different type of cancers, but not previously reported in human AT." (PMID 32714872, 2020). "Although this regulation pattern of RNA-protein interaction had been widely investigated, however, no study was reported between ZFAS1 and DDX21 in regard to cancers." (PMID 33202381, 2020).
cardiovascular disease (2 papers, 2021 to 2023). "Meanwhile, the roles of ZFAS1 in cardiovascular diseases were also reported." (PMID 33952724, 2021).